IL6 (interleukin 6)
Diseases named in the same sentence as IL6 in open-access papers (continued):
Sharing a sentence is not in itself a finding about the gene and the disease.
tumor (continued). "The EV release of bioactive molecules, such as platelet-derived growth factor (PDGF), hepatocyte growth factor (HGF), interleukin-6 (IL6), proteases, and miRNAs by CAFs into the extracellular matrix further supports their importance in cell–cell communication within the tumor microenvironment." (PMID 37760975, 2023). "It appears that eribulin is not particularly effective in patients with high IL-6 due to a poor tumor immune microenvironment." (PMID 37733188, 2023). "Correlation between VEGF/IL-6 ratio coefficients and the degree of regression of the tumor in IBC patients and IIIB stage BC without edema in the dynamics of neoadjuvant therapy." (PMID 36873124, 2023). "Moreover, knockdown of PKD3 in prostate cancer cells inhibited the secretion of tumor-promoting factors amongst them MMP-9, IL-6, Il-8 and GROα." (PMID 37293129, 2023). "Tumor markers (CEA and CA 19.9), as well as inflammatory markers—leukocytes, neutrophils, neutrophil/lymphocyte (N/L) index, platelets, fibrinogen, C-reactive protein (CRP), and interleukin 6 (IL6)— were also analyzed." (PMID 36917901, 2023). "In the hypoxic tumor micro-environment, pro-inflammatory factors such as tumor necrosis factor-α (TNF-α) and interleuin-6 (IL-6) were produced as a result of tissue damage and/or tumor necrosis, which might further activate the systemic inflammatory response." (PMID 37578602, 2023). "Moreover, IL-6 and TNF are also known to be tumor-promoting cytokines, with important roles in tumor initiation and progression." (PMID 38068717, 2023). "Importantly, APHC showed a significantly higher level of TGF-β1 and IL6 than ANHC, which probably contributed to enhanced accumulation of TAM-SPP1+ and the subsequent exhausted anti-tumor immune state." (PMID 37336873, 2023). "The indirect migration model evidenced that both primary tumor stiffness and secondary site ECM composition are essential in regulating expression of osteolytic factors PTHrP and IL‐6, and hence could affect osteolytic bone remodeling." (PMID 36351739, 2023). "IL-6 was found to be increased with PDAC, and was found to specifically suppress PPARalpha-regulated ketogenesis which may be correlated to tumor-induced cachexia." (PMID 36980608, 2023). "IL-6 leads to STAT3 activation, playing a pivotal role in tumor initiation and progression." (PMID 37047623, 2023). "The activation of the humoral immune system and the secretion of tumor cell-derived cytokines, such as tumor necrosis factor-alpha (TNF alpha), interferon-γ (IFN-γ), interleukin-1β (IL-1β), and interleukin-6 (IL-6) are part of the pathophysiology of cancer-related cachexia." (PMID 38067294, 2023). "IL-10 may decrease the production of proinflammatory cytokines such as IL-6, TNF-α, and IFN-γ and thus promote polarization of macrophages toward the protumorigenic M2 phenotype and thus ultimately enable tumor cells to evade immune surveillance." (PMID 38033495, 2023). "CXCL10, CXCL5, MMP1, CXCL12, CXCL11, CXCL2, STAT1, IL‐6 and TLR2 were hub genes, which may drive the homing of immune cells in tumours and promote immune cell differentiation." (PMID 36524848, 2023). "The cytokines secreted in BMM which are contributed to the pathogenesis of MM as IL6, VEGF and IGF activate their respective receptors expressed on MM cells through an important pathway, PI3K/AKT/mTOR, and promote tumor growth as well as resistance development to existing therapies." (PMID 37437037, 2023). "Moreover, pro-inflammatory mediators such as IFNγ, IL-1β, and IL-6 also induce EMT-TFs, leading to chronic inflammation in the tumor microenvironment, immune escape, and the acquisition of EMT-like features in tumor cells." (PMID 37370762, 2023). "Furthermore, oxaliplatin treatment enhanced secretion of pro-inflammatory cytokine IL-6 and IFN-γ, synergistically promoting HF-CAR-PMs-induced tumour cells killing." (PMID 37386139, 2023).
tumor (continued). "Moreover, the SASP cytokines, IL-6 and IL-8, have been shown to drive the transcription of both MMP genes and epithelial-to-mesenchymal transition (EMT), thus enhancing tumor invasion." (PMID 38275386, 2023). "Furthermore, CAFs can also limit CD8 + T cell recruitment and infiltration by producing IL-6, TGF-β, and CXCL12, and inhibiting their cytotoxic capabilities against tumor cells." (PMID 37723510, 2023). "Immunosuppressive agents directed against IL-6 (tocilizumab and sarilumab) in the treatment of irAEs were not evaluated in terms of their influence on tumor progression." (PMID 36981837, 2023). "On the other hand, tumor cells often express ligands for ICs that can be induced with oncogenic pathways and extrinsic factors in the TME such as the cytokines IFN-γ, IL-6, and TNF-α that contribute to the upregulation of PD-1 ligands 1 and L2 (PD-L1 and PD-L2) on tumor cells." (PMID 38258065, 2023). "The central role of IL-6 in promoting and supporting inflammation highlights its negative impact on the tumor." (PMID 36873124, 2023). "In inflammation and tumors, IL‐6‐mediated STAT3 can also participate in the autonomous migration of cells by regulating growth factors, forming an inflammation cascade amplification effect and tumor metastasis." (PMID 37382258, 2023). "Increased IL-6 and IL-8 levels can promote the EMT and tumor cell invasion." (PMID 36945046, 2023). "Furthermore, IL-6, IL-8, and IL-10 production by cells from the TME mediate pro-tumor functions of immune cells, such as neutrophils and macrophages." (PMID 37292196, 2023). "Anti-IL-6 treatment alone did not change the expression of F4/80 on splenic MDSCs compared to that in the tumor-bearing group, while the higher frequency of splenic F4/80+ MDSCs was induced after cryo-thermal therapy." (PMID 37108179, 2023). "Moreover, EVs can transfer pro-inflammatory factors, such as IL-6 and TNF-α, promoting an inflammatory milieu that supports tumor growth." (PMID 38052753, 2023). "Additionally, a positive feedback loop was described, including IL6/STAT3, IL1/NF-κB, and TNF/AP-1 signaling pathways, which maintain the state of inflammation in the tumor." (PMID 36825204, 2023). "Indeed, extracellular vesicles can contain as cargo a variety of angiogenic factors, such as ANG, IL-6, IL-8 and VEGF, or even mRNA, which can be incorporated by cells of the tumor microenvironment, changing their behavior." (PMID 37762073, 2023). "Notably, by 7 months old, the livers of HDAC3LCKO&IL-6−/− female mice had a considerable number of tumour nodules (91%, 10/11), whereas the livers of HDAC3LCKO&IL-6−/− male mice had only smaller tumour nodules (36%, 4/11)." (PMID 37752418, 2023). "It has been shown previously that the nonstructural protein of SFTSV can activate the tumor progression locus 2, which promotes the production of IL-10 to suppress the production of IL-6." (PMID 37143532, 2023). "Pre-adipocytes upregulates IL-6 secretion and promotes proliferation, migration, and invasion of MCF10DCIS.com cells, which can be attenuated by blocking IL6-mediated cross-linking in vitro and in a xenograft tumor model." (PMID 36880535, 2023). "In addition, we found that the tumor edge demonstrated increased pro-inflammatory and gliomagenic cytokines including TNF-α, IL-1β, and IL-6." (PMID 37752585, 2023). "Besides its oncogenic properties conferred on tumor cells through the JAK/STAT signaling pathway, IL-6 promotes PD-L1 expression in monocytes and macrophages in human HCC, contributing to immunosuppression in patients." (PMID 37762066, 2023). "SASP factors IL-6, IL-8, and CCL2 induce the recruitment of various antitumor immune cells, such as natural killer (NK) cells, M1 macrophages, and T helper 1 cells, which can exert a tumor clearance function." (PMID 38275386, 2023). "Here, PKD3 is required for the secretion of tumor promoting factors such as MMP9, IL-6 and IL-8." (PMID 37293129, 2023).
tumor (continued). "However, there are arguments that cytokines produced during thermal ablation, such as interleukin-6 (IL-6) and vascular endothelial growth factor (VEGF), promote tumor proliferation and metastasis." (PMID 38139799, 2023). "Moreover, in in vitro and in NOD/SCID mouse models, lenalidomide blocked the adverse effects of both IL-6 and TGF-β1, adjuvating the anti-tumor effect of anti-GD2 immunotherapy." (PMID 36980226, 2023). "Moreover, IL-6 in turn increased the EIF4A3 and CCL2 level within tumor cells in a positive feedback manner, further enhancing tumor cSERPINE2 biogenesis and promoting the recruitment of TAMs." (PMID 36797769, 2023). "IL-6/signal transducer and activator of transcription 3 (STAT3) signaling pathway was analyzed using qRT-PCR and Western blot in PC3 and DU145 cells and xenograft tumor tissues." (PMID 37576403, 2023). "According to this study, synchronous ARID1A loss and PIK3CA overactivation synergistically induced upregulation of IL-6, a cytokine that triggers and is triggered by the JAK/STAT pathway, thereby initiating a signaling cycle that promotes tumor cell growth and differentiation." (PMID 37627318, 2023). "The increased cytotoxicity of PDT mediated by the production of nitric oxide, interleukin-6 (IL-6), and tumor necrosis factor alpha was in turn achieved in the presence of non-resident macrophages with a strong anti-tumor phenotype (TNF-α)." (PMID 38201494, 2023). "Inhibition of PDGFRB signaling could result in the down-regulation of IL6 and TGFB1/2 in CAFs and suppressed expression of immune checkpoints in tumor cells, leading to immune cytotoxicity." (PMID 37658364, 2023). "Therefore, observably IL6 and IL10 act in a pro-tumor immunosuppressive loop in TME where both M2 and CSCs secrete them, supporting the growth of one another." (PMID 38035101, 2023). "Recent studies, using the xenograft mouse model of OS, demonstrated that tumor extracellular vesicle-educated MSCs may promote osteosarcoma progression through IL-6 production and lung metastasis through STAT3 activation in tumor cells." (PMID 37892917, 2023). "In contrast, expression of C3, SFRP2, STAT3, IL-6 and THY1 was increased in tumor-distal stroma." (PMID 37350578, 2023). "However, while among the anti-tumoral cytokines, TNF-α and IL-6 levels resulted both increased, IFN-γ level dropped in tumor mass of β3-AR antagonist-treated mice." (PMID 36854895, 2023). "The production of IL-6, capable of promoting tumor growth, was found to be increased in lymph node cells from tumor-bearing mice stimulated with CD3/CD28 antibodies compared to non-tumor-bearing mice in both LY2 and MOC2 HNSCC models." (PMID 37444444, 2023). "Likewise, the inhibition of catabolic pathways (IL-6, TNF-alpha), balanced with the stimulation of anabolic pathways (FoxO3a, p-AKT, p-mTOR, and P-GSK-3β), has occurred in the counteraction of tumor-induced cachexia." (PMID 38004420, 2023). "Tumor cells enhance the expression of chemical messengers such as chemokine C-C motif ligand (CCL)-2, CCL28, CCL18, TGFβ, cycloxygenase-2, prostaglandins, IL-1β, IL-6, IL-13, and human leukocyte antigen G." (PMID 38139779, 2023). "Similarly, cytokines in TME can also suggest the inflammatory state of the tumor and surrounding TME, and significant results have been obtained regarding the correlation of IL-6 and INF-γ levels with immunotherapy efficacy." (PMID 37002211, 2023). "Adversely, CAFs can release a variety of chemokines and cytokines, including interleukin-6 (IL-6), CC-chemokine ligand 2, and transforming growth factor (TGF), in order to attract inhibitory immune cell subsets in the tumor stroma, hence promoting immune evasion." (PMID 36813980, 2023). "In addition, it reduced IL-1β, IL-4, IL-6, IL-10, and IL-13 levels, down-regulated PI3K, ERK1/2, and up-regulated EGFR levels, improving the anti-tumor effects of the tumor suppressor microenvironment." (PMID 37397393, 2023).
tumor (continued). "The profiles of IL-6, CA-125, and HE4 levels based on tumor resectability." (PMID 37792745, 2023). "These infiltrated immune cells and solid tumor cells release tumor-progressing cytokines (IL-6, TNF-α, TGF-β), chemokines (CCL2, CCL5, CCL18, CXCL8, CXCL12), and growth factors (EGF, PGF, IGF-1, IGF-2, PDGF) that promote tumor microenvironment immunosuppressive." (PMID 37371075, 2023). "In addition, serum levels of TNF-α, IL-6 and VEGF also showed statistical difference in all above different tumor-related factors (all P < 0.001)." (PMID 37430251, 2023). "Based on our RNA-sequencing data, the Hallmark GSEA results indicated that BLACAT3 knockdown enriched EMT, IL6/JAK/STAT3, inflammatory response, KRAS, and TNFA/NF-κB pro-inflammatory signaling along with other gene sets related to tumor angiogenesis and metastasis." (PMID 37612524, 2023). "Bacteria sensing by myeloid cells promote calcineurin and NFAT-dependent IL-6 release and NFAT-dependent IL-6 promotes expression of B7-H3 by tumors and it inhibits CD8+ T cell-dependent anti-tumor immunity, while B7-H3 blockade elicits protective T cell responses." (PMID 36859240, 2023). "Taken together, in vivo data suggest that IL-6 blockade is a promising strategy in the context of ICI with suggested synergistic rather than detrimental effects on anti-tumour efficacy when given concomitantly." (PMID 37173424, 2023). "There was minimal calcification and central tumor necrosis, with absence of interleukin-6 expression on immunohistochemical study." (PMID 37730679, 2023). "In our study, MUC16 induced high expression of immunosuppressive factors such as IL-6, IL-8, PD-L1 and IDO1 in neutrophils, which might result in the weakness of tumor cell-killing ability for NK cells." (PMID 37644468, 2023). "Therefore, macrophage polarization to M2 type can be inhibited by inhibiting this signaling pathway, suppressing the expression of pro-tumor related cytokines such as IL-6, IL-10 and VEGF, and ultimately slowing down tumor disease progression." (PMID 37081874, 2023). "The incremental process of bone metastasis development is initiated by establishing a premetastatic niche at distant organs created by several tumor-derived factors (CCL2, IL6, lysyl oxidase (LOX), and Dickkopf WNT signaling pathway inhibitor 1 (DKK1)) of the primary tumor." (PMID 37296869, 2023). "A strong body of research indicates that cancer-associated fibroblasts (CAFs) and inflammatory factors in the TME, such as interleukin 6 (IL-6) and interferon-g (IFN-g), macrophages, and T cell-dependent immune responses, affected tumor growth through the HH signaling pathway." (PMID 37498396, 2023). "Mice receiving combined IL-6 and CTLA-4 blockade experienced consistent tumor regression by BLI." (PMID 36881480, 2023). "In addition to the tumor, we measured the expression profile of pro-inflammatory cytokines (IFN-γ, IFN-β, TNF-α, IL-12, and IL-6) in the spleen tissue as the main secondary host lymphoid compartment." (PMID 37901237, 2023). "Moreover, cytokines and growth factors secreted by CAFs, including TGF-β, IL-6, EGF, VEGF, and HGF, have been reported to facilitate tumor progression." (PMID 37853413, 2023). "Further examination of top 25 downregulated genes in ALDH- vs. ALDH+ cells upon XIST KD identified IL-6 and IL-8 as the top two genes most significantly inhibited in ALDH- bulk tumor cells, and these two cytokine genes are also downregulated, to a lesser extent, in ALDH+ CSCs." (PMID 36922677, 2023). "It suggests that IL6 is likely for neutrophil recruitment rather than activation of 8PN‐mediated neutrophil‐triggered tumor cytotoxicity." (PMID 37013960, 2023).
tumor (continued). "In addition, observably increased Th1 cytokines (IFN‐γ, IL‐12a and IL‐2) and decreased Th2 cytokines (IL‐6, IL‐10 and TGF‐β) in serums were also detected in tumor‐bearing mice post Pres and irradiation treatments." (PMID 37875395, 2023). "Secondly, we quantified release of cytokines (i.e., IFNγ, IL-10, IL-2, IL-6, TNFα, GM-CSF, IL-12p70, IL-1b and IL-8) and granzyme B by using the MSD platform in supernatants collected from the TDCC assay with the tumor cell lines SK-CO-1, MKN-45 and H2122 after 48 h." (PMID 38087365, 2023). "The secretion of IL-1β, IL-6, IL-8, SDF-1, and NFκB by CAFs contributes to immune cell recruitment that may contribute to tumor progression, cancer survival and drug resistance by creating a protective niche in the TME." (PMID 37174117, 2023). "In addition, vIL-6 transgenic mice developed IL-6-dependent MCD-like disease and supported tumor metastasis in a murine xenograft model." (PMID 37883374, 2023). "As we found, IFN-γ and IL-6 showed an upward trend in the tumor tissues overexpressing hsa_circ_0136666, while TGF-β had no significant change." (PMID 38093288, 2023). "Therefore, mRNA expressions of chemokines CCL2, CCL17 and CCL22, as well as IL-6, IL-18, TNF-α and IFN-γ, in tumor tissues and H22 cells were detected by RT-qPCR." (PMID 36674931, 2023). "Also in ovarian cancer, CAF secrete other secretory factors, including VEGF, IL-6, granulocyte colony-stimulating factor (G-CSF), CCL2/MCP-1, and CXCL8/IL-8, which are involved in tumorigenesis and lead to cancerous tumor growth." (PMID 37108425, 2023). "Current studies have shown that IL-6/JAK/STAT3, in addition to being expressed directly in tumor cells and promoting tumor cell proliferation, differentiation and metastasis, can also appear in macrophages and indirectly affect disease development and progression through macrophage M2 polarization." (PMID 37081874, 2023). "Interleukin-6 (IL-6), for example, triggers the activation of the Ras/Raf/MEK/MAPK, JAK/STAT3 and Phosphatidyl-Inositol 3-Kinase (PI3K/Akt) signaling pathways, protecting tumor cells from apoptosis." (PMID 36615316, 2022). "Thus, the increased expression of APCS, IL-6, and CXCL2 found in our patient cohort corresponds with improved immune cell function, and subsequent delays in VS tumor recurrence." (PMID 36195959, 2022). "Immune cells that surround BE and EAC, including myeloid-derived suppressor cells, T-regulatory cells and Th17 cells, secrete proinflammatory cytokines including IL-6, IL-19, TNFα and TGF-β, resulting in a tumor permissive environment that promotes tumor cell survival, proliferation and metastasis." (PMID 35267943, 2022). "The treatment may also trigger massive inflammatory and fibrotic reaction of the stroma orchestrated by cytokines including IL-1, IL-6, IL-10 and TGF-β, which can alter the tumor response to both radiation and chemotherapy." (PMID 36675979, 2022). "Therefore, inhibitors of IL-6/STAT3 signaling pathway are presently in clinical and/or preclinical development to inhibit tumor growth and relieve immunosuppression." (PMID 34976184, 2022). "Based on the tumor spheroids dimensions, the challenge with IL-6 on day 5 did not result in an obvious rescue of cell proliferation in the subsequent five days, in either the cultures where RV had been withdrawn or was continuously present." (PMID 35565270, 2022). "IL-6 staining showed an intensive cytoplasmatic staining pattern in tumours of cSI and cSII/III patients with no significant group differences (p = 0.232)." (PMID 35022523, 2022). "IL-6 seems to play the central role in the communication of noncancerous and cancer cells in the tumour." (PMID 35055153, 2022). "In addition, high levels of CXCL8/IL8, IL6, and MCP-1/CCL2 secretion promoted the migration of tumor cells and macrophage-like cells, exacerbating tumor progression." (PMID 36354566, 2022).